KRAS (KRas proto-oncogene, GTPase)
Diseases named in the same sentence as KRAS in open-access papers (continued):
Sharing a sentence is not in itself a finding about the gene and the disease.
breast cancer (continued). "However, KRAS is not considered a driver of human breast cancer development and its metastasis-specific recurrence in this model was unexpected." (PMID 32463822, 2020). "TGF-β may promote or inhibit tumor progression, whereas KRAS and EMT pathways are associated with worse prognosis, though there is still a lack of data for the role of KRAS in breast cancer." (PMID 32629782, 2020). "Thus, activation of the Ras/MAPK pathway, either through oncogenic KRAS activation, or other mechanisms, may drive MDSC recruitment in breast cancers in both mice and humans." (PMID 32634121, 2020). "Among the most frequently dysregulated pathways in breast cancer are the phosphatidylinositol 3-kinase (PI3K) pathway and the Ras/MAPK pathway, and therefore we chose to manipulate one component of each pathway (i.e., PTEN deletion and KRAS(G12V) expression) to promote pathway activation." (PMID 29848992, 2018). "We provide evidence for a role of the KRAS/BCL-XL interaction in the transition towards a CIC state together with the conceptual framework and tools to unravel its molecular basis, its regulation and biological outputs in breast cancer cell populations and CIC subsets." (PMID 29066722, 2017). "Interestingly, a double negative subtype (i.e. HER2− and KRAS−) showed poorer prognosis, similar to the poorer prognosis observed for triple-negative subtype in breast cancer." (PMID 23620766, 2013). "As compared to the presence of the variant allele among controls (17.3%), the increased frequency of the KRAS variant was confirmed in breast cancer cases from BRCA1 families (23.5%), but not among breast cancer cases from BRCA2 (13.5%) or non-BRCA1/2 families (15.8%)." (PMID 22436609, 2012). "In contrast to Hollestelle and colleagues, who found increased frequency of the KRAS variant among cases from BRCA1 positive families, we did not observe an association between the KRAS variant and either cases from BRCA1, BRCA2 or non-BRCA breast cancer families." (PMID 22436609, 2012). "Interestingly, in breast cancer, ERK activation was less pronounced in MDA-MB-231, a cell line harbouring KRAS G38A and BRAF G464V mutations, compared with the non-transformed epithelial cell line MCF10a." (PMID 21730974, 2011). "In addition, unlike breast cancer, several aberrations are able to drive trastuzumab resistance in GC, including mutations in EGFR, MET, KRAS, PI3K, and PTEN genes, as well as EGFR, MET, and KRAS amplifications." (PMID 33916206, 2021). "The lack of KRAS involvement in breast cancer cells was further supported by treating CTR and TIS cells with RMC-6236, a pan-KRAS inhibitor, which did not elicit significant sensitivity in either condition." (PMID 40312750, 2025). "Consistent with prior reports of differential usage of glutamine in mutant KRAS versus wild-type KRAS cancers, we found that mutant KRAS cell lines, but not wild-type KRAS PDA, lung, and breast cancer, were sensitized to ß-lap upon pre-treatment with BPTES." (PMID 26462257, 2015). "Given that MDA MB 231 breast cancer cells express activated G13D KRas and moderately activated G464V BRaf, while MDA MB 435 melanoma cells express oncogenic V600E BRaf, increased KRas signal output was not the result of selection for cells with de novo Ras/MAPK pathway mutations." (PMID 31152052, 2019).
metastatic colorectal cancer (424 papers, 2007 to 2026). "The method is illustrated by a re-analysis of a trial investigating treatment interactions with KRAS mutation type in patients with metastatic colorectal cancer." (PMID 41731731, 2026). "KRAS mutations are present in approximately 35–45% of metastatic colorectal cancer cases, with NRAS mutations occurring in a smaller subset." (PMID 40805233, 2025). "The majority of metastatic colorectal cancer patients who bear MMR proficient tumors or tumors with KRAS mutations (besides KRAS G12C) have few options available besides chemotherapy and anti-angiogenic agents." (PMID 40061138, 2025). "This multicenter, epidemiological observational study represents the most extensive investigation of the frequency, anatomical distribution, and mutation spectrum of KRAS mutations in metastatic colorectal cancer (mCRC) patients across Turkey." (PMID 40282985, 2025). "We investigated genetic mutations in 142 samples from primary tumours of 39 KRAS wild‐type metastatic colorectal cancer (CRC) patients receiving anti‐EGFR therapy." (PMID 40302146, 2025). "The inhibitor WNT974 was studied in combination with encorafenib and cetuximab in a phase Ib/II trial of patients with BRAF V600E mutated, KRAS wild type metastatic colorectal cancer." (PMID 40061138, 2025). "Preliminary results show that onvansertib combined with FOLFIRI/bevacizumab has a manageable safety profile and good efficacy in the second-line treatment of patients with KRAS-mutated metastatic colorectal cancer." (PMID 41458961, 2025). "In metastatic colorectal cancer, KRAS mutations occur in approximately 35–40% of cases in Asia, 40–50% in Europe, and 35–45% in Latin America." (PMID 40282985, 2025). "Downregulation of let-7 in metastatic colorectal cancer has been linked to resistance to cetuximab, particularly in tumors harboring KRAS mutations and activated mitogen-activated protein kinase (MAPK) signaling." (PMID 41425255, 2025). "KRAS mutation analysis is routinely performed in all metastatic colorectal cancer patients in Turkey." (PMID 40282985, 2025). "Future studies addressing these limitations are warranted to provide a more comprehensive understanding of KRAS mutations in metastatic colorectal cancer." (PMID 40282985, 2025). "For instance, KRAS/NRAS mutations in metastatic colorectal cancer (mCRC) are associated with resistance to EGFR-targeted therapies, such as cetuximab and panitumumab." (PMID 40740242, 2025). "The next two studies focused on cost-effectiveness analysis for treatments developed for patients with metastatic colorectal cancer with mutated KRAS G12C." (PMID 41301043, 2025). "Mutations in KRAS occur in approximately 45% of patients with metastatic colorectal cancer (mCRC), making it one of the most frequently mutated oncogenes in this cancer type." (PMID 40740242, 2025). "In metastatic colorectal cancer (mCRC), KRAS and BRAF mutations are well-known markers of resistance and poor prognosis in patients receiving anti-epidermal growth factor receptor (EGFR) monoclonal antibodies." (PMID 40279317, 2025). "KRAS mutations in metastatic colorectal cancer (mCRC) are used as predictive biomarkers to select therapy with EGFR monoclonal antibodies (mAbs)." (PMID 38402342, 2024). "In metastatic colorectal cancer patients harboring KRAS mutations (KRAS G12C), treatment with EGFR inhibitors or monoclonal antibodies yields minimal benefit." (PMID 39770538, 2024). "The clinical impact of the KRAS mutational signature differs in metastatic colorectal cancer, for example." (PMID 39372214, 2024). "A link between KRAS gene mutations and the therapeutic response was initially observed in individuals with metastatic colorectal cancer who were treated with anti-epidermal growth factor receptor (EGFR) agents." (PMID 39673361, 2024).
metastatic colorectal cancer (continued). "A phase Ib/II study on avutometinib and cetuximab aims to assess the safety and efficacy of avutometinib combined with cetuximab in KRAS-mutated metastatic colorectal cancer patients." (PMID 38790167, 2024). "The study is testing its combination with cetuximab, an EGFR inhibitor, in KRAS-mutated metastatic colorectal cancer patients." (PMID 38790167, 2024). "Determining the RAS (KRAS/NRAS) mutational status on a tumor biopsy is mandatory to guide the best treatment recommendation in metastatic colorectal cancer (mCRC)." (PMID 38642257, 2024). "The purpose of this study was to assess the ability of metabolic parameters, radiomic features, PET-CT, and clinicopathological data to detect EGFR, BRAF, and KRAS mutation status in metastatic colorectal cancer patients (mCRC)." (PMID 39722096, 2024). "The objective of this study was to evaluate the predictive value of 18F-fluorodeoxyglucose [18F]FDG positron emission tomography (PET-CT) radiomic parameters in relation to KRAS/BRAF/EGFR mutations in patients with metastatic colorectal cancer (mCRC)." (PMID 39722096, 2024). "RAS (KRAS/NRAS) mutational status on a tumor biopsy is mandatory to guide the best treatment in metastatic colorectal cancer (mCRC)." (PMID 38642257, 2024). "KRAS mutation in tumor tissue is a well-known predictor of resistance to the treatment of anti-EGFR antibodies in metastatic colorectal cancers (mCRC)." (PMID 37511664, 2023). "BRAF mutations in metastatic colorectal cancer are more frequently observed in older individuals (>70 years), current or former smokers, white patients, females, and those with KRAS wild-type tumors." (PMID 37686423, 2023). "In this review, we aim to clarify the prognostic significance of the KRAS p.G12C mutation in metastatic colorectal cancer, emphasizing its potential as a promising therapeutic target." (PMID 37509241, 2023). "The KRAS p.G12C mutation holds significant clinical importance in patients with metastatic colorectal cancer." (PMID 37509241, 2023). "The detection of KRAS mutations in tumor tissue is a well-known predictor of resistance to the treatment of anti-epidermal growth factor receptor (EGFR) antibodies in metastatic colorectal cancer (mCRC)." (PMID 37511664, 2023). "A combination of real-world evidence and a reanalysis of phase 3 clinical trial data unveils KRAS codon G12 mutations as a biomarker of resistance to trifluridine/tipiracil in metastatic colorectal cancer." (PMID 36864254, 2023). "Although approximately half of all metastatic colorectal cancers (mCRCs) harbour mutations in KRAS or NRAS, hardly any progress has been made regarding targeted treatment for this group over the last few years." (PMID 37604687, 2023). "The present study was motivated by conflicting clinical data regarding the prognostic impact of Kirsten rat sarcoma viral oncogene homolog (KRAS) mutation in patients with metastatic colorectal cancer (mCRC)." (PMID 36788889, 2023). "Cetuximab, as a first-line treatment, reduced the risk for patients with metastatic colorectal cancer who exhibited wild-type progression of KRAS." (PMID 38201315, 2023). "We present the case of a 46-year-old man of Ashkenazi Jewish ancestry who was diagnosed with KRAS-mutated metastatic colorectal cancer." (PMID 38023256, 2023). "BRAF and KRAS mutations have been reported to occur in ∼10% and 44% of patients with metastatic colorectal cancer, which is similar to frequency (KRAS: 46%; BRAF: 11.2%; NRAS: 3%) observed in our sample cohort." (PMID 37483495, 2023). "A multicentre retrospective review from Japan published in 2021 compared survival in patients with KRAS G12C mutant metastatic colorectal cancers and those with other KRAS mutations." (PMID 38067288, 2023). "In this study, we showed that R9VH36 also inhibits cell viability on the other KRAS mutations metastatic colorectal cancer, SW480 (G12V)." (PMID 35578244, 2022).
metastatic colorectal cancer (continued). "In 2016, a seminal study demonstrated that adoptive transfer of expanded TILs specific for Gly 12 to Asp mutation in KRAS (KRAS-G12D) lead to tumor regression in a patient with metastatic colorectal cancer." (PMID 35222422, 2022). "Multiple clinical trials with cetuximab in metastatic colorectal cancer observed a significant association between KRAS mutant status and cetuximab efficacy." (PMID 35054865, 2022). "The RAS gene is often mutated in metastatic colorectal cancer, and the most mutated gene is the Kirsten Ras (KRAS) gene." (PMID 36339570, 2022). "Metastatic colorectal cancer (mCRC) harbors several mutations with different prognostic and predictive values; KRAS, NRAS, and BRAF mutations are the best known." (PMID 34988329, 2021). "One of such critical steps is the understanding of the mechanism and development of therapeutic targets against metastatic colorectal cancers bearing the KRAS mutation." (PMID 34944853, 2021). "KRAS mutations in metastatic colorectal cancer (mCRC) define a subset of tumors that have primary resistance to anti-EGFR-based therapy." (PMID 34660299, 2021). "This particular study involved genetic manipulation of the fly genome to induce mutations specific to KRAS-mutant metastatic colorectal cancer." (PMID 34336681, 2021). "In other words, in the majority of patients with metastatic colorectal cancer, the type of oncological and surgical management is determined by the KRAS mutation status analyzed in the primary tumor." (PMID 33946899, 2021). "This study examined the cost-effectiveness of preventive skin care for skin-toxicity caused by panitumumab in third-line therapy for KRAS wild type metastatic colorectal cancer from the perspective of the Japanese healthcare payer." (PMID 34593037, 2021). "In light of these findings, the American Society of Clinical Oncology (ASCO) recommends testing both the EGFR and KRAS mutation status in patients with metastatic colorectal cancer who are candidates for anti-EGFR antibody therapy." (PMID 33801965, 2021). "It was shown to selectively inhibit metastatic colorectal cancer with the KRAS (Kirsten rat sarcoma viral oncogene homolog) mutation, inhibiting cell proliferation by inactivating both RAS/ERK and AKT/mTOR signaling." (PMID 34671273, 2021). "Somatic KRAS mutations occur in approximately half of the patients with metastatic colorectal cancer (mCRC)." (PMID 34820593, 2021). "Here, we evaluated how clinical features like tumor load and overall survival differ between patients with metastatic colorectal cancer (mCRC) carrying distinct somatic KRAS G12, G13, Q61, K117, or A146 mutations." (PMID 34820593, 2021). "The FDA updated the label of panitumumab for the treatment of metastatic colorectal cancer, including information about KRAS mutations: When the KRAS mutation in codon 12 or 13 was found, panitumumab showed no therapeutic effect." (PMID 32793499, 2020). "KRAS mutation has recently been shown to be a prognostic biomarker of worse survival outcomes in metastatic colorectal cancer in a large meta-analysis of first line randomised chemotherapy trials, an analogous situation to those referred for SBRT." (PMID 32866563, 2020). "We analyzed a cohort of forty chemorefractory metastatic colorectal cancer patients, of whom twenty-six KRAS mutated, treated with regorafenib, all as the third line of treatment." (PMID 32962309, 2020). "KRAS mutation is a confirmed predictive biomarker for anti-EGFR monoclonal antibody therapy response for metastatic colorectal cancer." (PMID 31952366, 2020). "We analyzed serial plasma samples (n = 80) from ten metastatic colorectal cancer (mCRC) patients with a known KRAS mutation in their primary tumor." (PMID 33237900, 2020). "This study suggests that Jordanian patients with metastatic colorectal cancer have a higher rate of KRAS outside exon 2 and NRAS mutations when compared to the literature." (PMID 31881025, 2019).
metastatic colorectal cancer (continued). "We assessed 72 consecutive patients with a diagnosis of metastatic colorectal cancer (mCRC) using IdyllaTM Biocartis, a fully automated platform that evaluates the most frequent mutations of KRAS, NRAS and BRAF genes." (PMID 31597339, 2019). "The authors examined the expression level of three different β4 polymorphisms in HER3-negative/KRAS WT metastatic colorectal cancer from patients receiving irinotecan/cetuximab." (PMID 31109009, 2019). "In metastatic colorectal cancer (mCRC), KRAS proto-oncogene, GTPase (KRAS) mutation is responsible for primary resistance to EGFR blockage." (PMID 31480647, 2019). "In conclusion, this analysis confirms that FCGR2A H/H polymorphism in patients with wild‐type KRAS metastatic colorectal cancer treated with cetuximab is associated with significantly longer OS without affecting toxicity profiles." (PMID 30318772, 2018). "As it was shown in metastatic colorectal cancer, the KRAS G12D mutation can be successfully targeted by specific tumor-infiltrating lymphocytes." (PMID 28670312, 2017). "Activating mutations in the KRAS gene, found in approximately 53% of metastatic colorectal cancer (mCRC) cases, can render epidermal growth factor receptor (EGFR) inhibitors ineffective." (PMID 28797274, 2017). "We analyzed KRAS mutations in single CTCs from patients with metastatic colorectal cancer (mCRC) using a new single-cell picking system." (PMID 28468669, 2017). "It has been shown in a previous study in metastatic colorectal cancer patients that the occurrence of EGFRI-induced skin rash was significantly associated with OS in patients with mutations in codon 12 of KRAS in tumor cells." (PMID 28456787, 2017). "For example, the National Comprehensive Cancer Network (NCCN) guidelines recommend testing for the KRAS alterations as a part of the initial diagnostic check for metastatic colorectal cancer (CRC)." (PMID 28796802, 2017). "We previously reported a patient with synchronous BRAF-mutated metastatic melanoma and BRAF wt /KRAS G12D-metastatic colorectal cancer (CRC), whose CRC relapsed and progressed when treated with the BRAF inhibitor dabrafenib (GSK2118436)." (PMID 28659148, 2017). "Testing for KRAS mutations in metastatic colorectal cancer (mCRC) on formalin-fixed, paraffin embedded (FFPE) tumor tissue has become standard of care." (PMID 28201998, 2017). "A phase II trial in refractory metastatic colorectal cancer patients suggested that 53% of those who reported stable disease had KRAS-mutated tumour." (PMID 28255900, 2017). "In another study, chemorefractory wild-type KRAS metastatic colorectal cancer patients harboring the IGF1 rs2946834 variant A/A genotype had a significantly higher response rate to cetuximab (50%) compared to those with the A/G genotype (0%)." (PMID 27144430, 2016). "Similar to the result of the present study, high levels of serum HGF was associated with poor prognosis in KRAS wild-type patients with metastatic colorectal cancer." (PMID 26716644, 2016). "Metastatic colorectal cancer (CRC) patients with v‐Ki‐ras2 Kirsten rat sarcoma viral oncogene homolog (KRAS) mutations are resistant to monoclonal antibody that targets the epidermal growth factor receptor such as cetuximab." (PMID 26715098, 2016). "KRAS mutations have become routinely used as molecular biomarkers in clinical practice for management and monitoring of metastatic colorectal cancer patients." (PMID 27043547, 2016). "KRAS exon 2 mutations are predictive of resistance to epidermal growth factor receptor-directed monoclonal antibodies in patients with metastatic colorectal cancer." (PMID 26573425, 2016). "Mutation analysis of KRAS is needed before starting treatment with monoclonal anti-EGFR antibodies in patients with metastatic colorectal cancer (mCRC)." (PMID 26812617, 2016).